SPTSSA (serine palmitoyltransferase small subunit A)
Description:
Component of the serine palmitoyltransferase multisubunit enzyme (SPT) that catalyzes the initial and rate-limiting step in sphingolipid biosynthesis by condensing L-serine and activated acyl-CoA (most commonly palmitoyl-CoA) to form long-chain bases. The SPT complex is composed of SPTLC1, SPTLC2 or SPTLC3 and SPTSSA or SPTSSB. Within this complex, the heterodimer consisting of SPTLC1 and SPTLC2/SPTLC3 forms the catalytic core. Within the SPT complex, SPTSSA stimulates the catalytic activity and plays a role in substrate specificity, which depends upon the overall complex composition. The SPTLC1-SPTLC2-SPTSSA complex shows a strong preference for C16-CoA substrate, while the SPTLC1-SPTLC3-SPTSSA isozyme uses both C14-CoA and C16-CoA as substrates, with a slight preference for C14-CoA. Independently of its action as a SPT component, may be involved in MBOAT7 localization to mitochondria-associated membranes, a membrane bridge between the endoplasmic reticulum and mitochondria, may hence affect MBOAT7-catalyzed incorporation of arachidonic acid into phosphatidylinositol.
Synonyms: ssSPTa; C14orf147; SPG90A; SPG90B
Tractability: Small molecule: a structure with a bound ligand is known. Antibody: UniProt predicts a signal peptide or a membrane-spanning region.
Gene: Protein-coding gene on chromosome 14 (34,432,788 to 34,462,240, reverse strand). Ensembl gene ENSG00000165389.
Subcellular location: Endoplasmic reticulum membrane
Pathways (Reactome):
Metabolism: Sphingolipid de novo biosynthesis
Gene Ontology:
Molecular function: protein binding; serine C-palmitoyltransferase activity
Biological process: ceramide biosynthetic process; glycosphingolipid biosynthetic process; intracellular protein localization; sphingomyelin biosynthetic process; sphingosine biosynthetic process; sphingolipid biosynthetic process; sphingolipid metabolic process
Cellular component: cytoplasmic side of endoplasmic reticulum membrane; endoplasmic reticulum; endoplasmic reticulum membrane; serine palmitoyltransferase complex
Genetic constraint (gnomAD): Loss-of-function variants: 7 observed, 3.97 expected, observed/expected ratio (o/e) 1.76, 90% interval 0.88 to 1.95. That is too few expected variants to judge how well the gene tolerates losing a copy. Missense variants: 89 observed, 62.63 expected, observed/expected ratio (o/e) 1.42, 90% interval 1.2 to 1.69. Synonymous variants: 33 observed, 25.04 expected, observed/expected ratio (o/e) 1.32, 90% interval 1 to 1.75.
Homologues: Orthologues: chimpanzee SPTSSA (100% identical), macaque SPTSSA (100% identical), dog SPTSSA (99% identical), mouse Sptssa (99% identical), rat Sptssa (99% identical), guinea pig SPTSSA (97% identical), pig SPTSSA (97% identical), tropical clawed frog sptssa (85% identical), zebrafish sptssa (79% identical), Drosophila melanogaster CG34194 (25% identical), Drosophila melanogaster CG34293 (23% identical). Paralogues in human: SPTSSB (41% identical).
Diseases named in the same sentence as SPTSSA in open-access papers:
SPTSSA is named in the same sentence as 10 diseases in open-access papers, as found by Europe PMC text mining. Sharing a sentence is not in itself a finding about the gene and the disease. The quoted sentences say what the papers report.
glioma (2 papers, 2022 to 2024). A benign or malignant brain and spinal cord tumor that arises from glial cells (astrocytes, oligodendrocytes, ependymal cells). "SPTSSA was highly expressed in gliomas and significantly correlated with infiltrating immune cells and overall survival." (PMID 38779100, 2024). "In the current study, we used bioinformatics analysis on GEPIA and CGGA databases and identified SPTSSA expression correlating with the prognosis of glioma patients." (PMID 36062185, 2022). "Our findings revealed that in contrast to low-grade (I and II) gliomas, high-grade (III and IV) gliomas have highly expressed SPTSSA." (PMID 36062185, 2022). "To estimate the expression of SPTSSA in glioma tissues, we used IHC." (PMID 36062185, 2022).
clear cell renal cell carcinoma (1 paper, 2020). "In a clear cell renal cell carcinoma (ccRCC) study, bioinformatics analysis revealed that 10 genes, including SPTSSA, significantly coregulated ccRCC with SPTLC1, and the low expression of SPTLC1 was significantly correlated with the disease progression and poor prognosis of ccRCC." (PMID 33042807, 2020).
Farber Disease (1 paper, 2023). "The SPTLC1- and SPTSSA-associated disorders represent the former case, while Farber Disease (deficiency of ceramidase encoded by ASAH1) corresponds to an example of the latter case." (PMID 36875645, 2023).
sarcopenia (1 paper, 2025). Progressive decline in muscle mass due to aging which results in decreased functional capacity of muscles. "The findings demonstrated that FOXO1, CTH, HSD11B1, GSTK1, and SPTSSA were the five sarcopenia model genes (SMGs) that were included in the LASSO regression model." (PMID 41325398, 2025). "LASSO regression identified CTH and IDI1 for IPF, and FOXO1, CTH, HSD11B1, GSTK1, and SPTSSA for sarcopenia." (PMID 41325398, 2025). "In general, the validity of the diagnostic models was evident with the values of the predictive models of IPF; CTH, and IDI1 as well as the models of sarcopenia; FOFOXO1, CTH, HSD11B, GSTK1, and SPTSSA." (PMID 41325398, 2025).
Spastic paraplegia (1 paper, 2025). Complete loss of the ability to move the lower limbs accompanied by spasticity of the lower limbs. "Two individuals with de novo SPTSSA variants and another with an inherited biallelic SPTSSA variant were identified, where individuals presented a highly variable spastic paraplegia and motor impairment syndrome with hearing loss as a variable feature in 2/3 of affected individuals." (PMID 41191133, 2025).
uveal melanoma (1 paper, 2025). A melanoma derived from melanocytes of the uveal tract. "To extend this analysis further and to orthogonally computationally validate CDS2, RIC8A and SPTSSA, and to identify further candidates, including nonparalog genes, we adopted an additional approach to identify gene vulnerabilities that were specific to uveal melanoma." (PMID 40615675, 2025).
cancer (2 papers, 2020 to 2022). A tumor composed of atypical neoplastic, often pleomorphic cells that invade other tissues. "However, 2 of the 17-metabolism risk genes, including SPTSSA and ARSF have not been studied in cancers." (PMID 33042807, 2020).
tumor (2 papers, 2022 to 2024). "Finally, we showed that SPTSSA expression was significantly associated with tumor-infiltrating immune cells and overall survival via IHC." (PMID 36062185, 2022). "We used CIBERSORT analysis to evaluate the correlation of SPTSSA expression with tumor-infiltrating immune cells (TIICs)." (PMID 36062185, 2022). "The SPTSSA expression being significantly correlated with numbers of tumor-infiltrating dendritic cells, neutrophils, and macrophages was revealed clearly." (PMID 36062185, 2022). "To further shed light on the potential function of SPTSSA in GBM progression, we used both CIBERSORT and TIMER to correlate tumor-infiltrating immune cells with SPTSSA expression in GBM." (PMID 36062185, 2022). "Genes involved in glycolysis (ALDOA, LDHA, PGK1, PFKL, PGM1) and other metabolic processes (GPX4, PRDX4, ACO2, ASPH, IDH2, SQLE, NPC2, SPTSSA) were upregulated in primary tumor cells, suggesting that the metabolism in primary tumors was distinct from that in their matched metastasis." (PMID 39225101, 2024). "Finally, we provided evidence that SPTSSA expression was correlated with tumor immune infiltrates by CIBERSORT, TIMER, IHC, and IF." (PMID 36062185, 2022).
SPTSSA also shares sentences with these, for which no sentence is quoted: acne (1 paper); glioblastoma (1).